DNLZ (DNL-type zinc finger)
Description:
May function as a co-chaperone towards HSPA9/mortalin which, by itself, is prone to self-aggregation.
Synonyms: HEP1; C9orf151; RP11-413M3.2; ZIM17; bA413M3.2; TIMM15; HEP
Tractability: PROTAC: its protein half-life has been measured.
Gene: Protein-coding gene on chromosome 9 (136,359,480 to 136,363,744, reverse strand). Ensembl gene ENSG00000213221.
Subcellular location: Mitochondrion
Subcellular location (Human Protein Atlas): Mitochondria; Nucleoplasm
Gene Ontology:
Molecular function: Hsp70 protein binding; protein-folding chaperone binding; zinc ion binding
Biological process: chaperone-mediated protein complex assembly; protein folding; protein import into mitochondrial matrix; protein stabilization
Cellular component: cytosol; mitochondrion; nucleus
Genetic constraint (gnomAD): Loss-of-function variants: 9 observed, 5.1 expected, observed/expected ratio (o/e) 1.77, 90% interval 0.96 to 1.96. That is too few expected variants to judge how well the gene tolerates losing a copy. Missense variants: 163 observed, 117.26 expected, observed/expected ratio (o/e) 1.39, 90% interval 1.22 to 1.58. Synonymous variants: 80 observed, 52.97 expected, observed/expected ratio (o/e) 1.51, 90% interval 1.26 to 1.81.
Homologues: Orthologues: chimpanzee DNLZ (98% identical), macaque DNLZ (93% identical), pig DNLZ (73% identical), mouse Dnlz (72% identical), rat Dnlz (70% identical), guinea pig DNLZ (66% identical), dog DNLZ (55% identical), zebrafish dnlz (42% identical), tropical clawed frog dnlz (40% identical), Drosophila melanogaster CG12379 (34% identical), Caenorhabditis elegans F53A3.7 (30% identical), Drosophila melanogaster CG8206 (25% identical).
Diseases named in the same sentence as DNLZ in open-access papers:
DNLZ is named in the same sentence as 18 diseases in open-access papers, as found by Europe PMC text mining. Sharing a sentence is not in itself a finding about the gene and the disease. The quoted sentences say what the papers report.
morbid obesity (1 paper, 2023). An excess of body weight, normally defined as an individual with a body mass index greater than 35 or a body weight greater than one hundred percent of ideal body weight. "According to the analysis of bulk RNA-seq data, three significantly differentially expressed TWAS-identified genes were observed when comparing individuals with type 2 diabetes and non-diabetic individuals with morbid obesity: PABPC4 (p=0.004); HAUS6 (p=0.011); and DNLZ (p=0.013)." (PMID 37540242, 2023).
DNLZ also shares sentences with these, for which no sentence is quoted: hepatocellular carcinoma (3 papers); infection (3); liver cancer (3); iron metabolism disorders (2); chronic hepatitis (1); Cirrhosis (1); colon cancer (1); endotoxemia (1); hemochromatosis (1); hepatoid adenocarcinoma (1); iron overload (1); metabolic disease (1); metastatic carcinoma (1); schizoaffective disorder (1); tumor (1); type 2 diabetes (1); viral infection (1).